EPHB2 (EPH receptor B2)
Diseases named in the same sentence as EPHB2 in open-access papers (continued):
Sharing a sentence is not in itself a finding about the gene and the disease.
Obesity (4 papers, 2021 to 2024). Accumulation of substantial excess body fat. "(2022) investigated the role of EphB2/ephrin-B1 signaling in the development and progression of obesity-associated CRC." (PMID 38651144, 2024). "The association between obesity and EphB2 mutations should be analysed in future studies." (PMID 35949596, 2022). "Obesity also results in EphB2 downregulation, leading to the more rapid cancer development and progression observed in obese mice and humans." (PMID 35949596, 2022). "It was found that ephrin-B1 expression at the top of the crypt was downregulated in obesity and that the dysregulated EphB2/ephrin-B1 signalling may disrupt cell apoptosis and carcinogenesis." (PMID 35949596, 2022).
ovarian carcinoma (4 papers, 2007 to 2019). A malignant neoplasm originating from the surface ovarian epithelium. "Amongst them, EPHB2 has only been reported twice as a biomarker with negative prognostic value in ovarian carcinoma." (PMID 19112514, 2008).
autism (3 papers, 2018 to 2022). Persistent deficits in social interaction and communication and interaction as well as a markedly restricted repertoire of activity and interest as well as repetitive patterns of behavior. "Cg04112471 is annotated to SPSB4 (SplA/Ryanodine Receptor Domain And SOCS Box Containing 4), a gene regulating EphB2-dependent cell repulsive responses that has also been associated with autism." (PMID 33494854, 2022). "As such, the EPHB2 Q857X mutation might produce ASD and autism-associated symptoms through a dominant interfering or gain-of-function effect during neurotypical development, and future studies with EphB2 Q857X knock-in mice will be important to assess that possibility." (PMID 33649502, 2021). "Interestingly, EphB2+/− females, but not males, displayed repetitive behavior, a core symptom of autism, as well as autism-associated symptoms, such as motor hyperactivity and learning and memory deficits." (PMID 33649502, 2021).
Barrett esophagus (3 papers, 2022 to 2025). Esophageal lesion lined with columnar metaplastic epithelium which is flat or villiform. "In esophageal adenocarcinoma (EAC), its influence is also evident in the BE-EAC sequence, being regulated by the Ephrin B2 Receptor Tyrosine Kinase (EphB2)." (PMID 40149421, 2025).
breast tumor (3 papers, 2022 to 2024). "While the EphB2 protein was detected in all normal tissue samples, it was shown to be overexpressed in 51% of breast tumours, and patients with higher EphB2 expression had a worse prognosis." (PMID 36830852, 2023). "For example, some breast tumor-related genes such as EPHB2 (Ephrin type-B receptor 2) and LONP1 (Lon Peptidase 1) present altered methylation under PAH and NO2 exposures." (PMID 35454102, 2022).
colitis (3 papers, 2021 to 2025). Inflammation of the colon. "The ubiquitination of EPHB2 participated in macroautophagy/autophagy activation in the DSS-induced colitis model." (PMID 35027539, 2022). "Compared with EVs, EphB2-EVs significantly ameliorated the clinical symptoms of colitis in rats, accompanied by the amelioration of inflammatory response in the colon tissue." (PMID 33722292, 2021). "In the present study, we systematically studied the therapeutic effects of EphB2-EVs on DSS-induced colitis rats and its potential mechanism." (PMID 33722292, 2021). "We analyzed the EphB2-EVs ability of colonic targeting in a DSS-induced colitis model by using confocal microscope and WB." (PMID 33722292, 2021). "Therefore, this signaling pathway was also investigated to further ascertain the immunomodulatory mechanism of EphB2-EVs during colitis." (PMID 33722292, 2021). "Therefore, we speculated that EphB2-EVs may be able to relieve DSS-induced colitis in rats." (PMID 33722292, 2021). "Compared to EVs, EphB2-EVs remarkably restored the intestinal mucosal barrier and attenuated the inflammatory response and oxidative stress in DSS-induced colitis rats." (PMID 33722292, 2021). "Altogether, EphB2-EVs robustly mitigate colon tissues injury and TJs destruction in DSS-induced colitis rats." (PMID 33722292, 2021). "Our results suggest that EphB2-EVs have high colonic targeting ability and could mitigate DSS-induced colitis via maintaining colonic immune homeostasis." (PMID 33722292, 2021).
colon adenoma (3 papers, 2015 to 2024). An adenoma that arises from the colon. "Our findings are consistent with those in a prior study that showed increased expression of EphB2/B3 and loss of ephrinB1/B2 expression in colon adenomas of Apcmin/+ mice." (PMID 26528816, 2015).
epilepsy (3 papers, 2017 to 2021). A brain disorder characterized by episodes of abnormally increased neuronal discharge resulting in transient episodes of sensory or motor neurological dysfunction, or psychic dysfunction. "During the activation, various genes of our predicted EPH family have been identified to promote such biological processes, validating the crucial role of EPH family including our predicted genes EPHA3, EPHA4, EPHA5, EPHA7, and EPHB2 during epilepsy." (PMID 28255556, 2017). "Together, the regulation of synaptic function may be closely related to EphB2-NMDAR interaction in epilepsy." (PMID 35069111, 2021).
invasive carcinoma (3 papers, 2010 to 2020). A carcinoma that is not confined to the epithelium, and has spread to the surrounding stroma. "Recently EPHB2 was found to be a target of TGFβ3-mediated invasion and migration which is in line with increased EPHB2 protein levels in invasive carcinomas." (PMID 26870995, 2016). "Interestingly, in contrast to EPHB2, the expression of EPHA3, a member of another subclass of the ephrin receptors, was significantly decreased in invasive carcinoma samples." (PMID 32899940, 2020).
liver disease (3 papers, 2020 to 2024). "Our observation also suggests that restoring NMD activity may show a protective effect in liver diseases by suppressing the expression of disease-related genes, such as Robo1 and Ephb2." (PMID 39456836, 2024).
malignant mesothelioma (3 papers, 2020 to 2025). A malignant neoplasm of the pleura or peritoneum, arising from mesothelial cells. "EphB2 expression was significantly high in malignant mesothelioma compared to matched normal peritoneum." (PMID 40943224, 2025). "EphB2 was reported to be overexpressed in malignant mesothelioma (MM) cell lines and tumor tissues." (PMID 35223830, 2022).
Stroke (3 papers, 2019 to 2023). Sudden impairment of blood flow to a part of the brain due to occlusion or rupture of an artery to the brain. "Another aspect of the EphB/ephrin-B system is its capacity to modulate immune responses, a feature which may provide an alternative explanation for the observed less severe stroke response of Ephb2-deficient mice." (PMID 30722785, 2019). "Histological, neurofunctional and transcriptome analyses indicated an increase in EphB2 phosphorylation under these conditions and attenuated progression of stroke in Ephb2−/− mice." (PMID 30722785, 2019). "Given that brain tissue protection in Ephb2−/− mice is already detectable during the first 6 h of a stroke, we reasoned that EphB2-dependent signaling might be involved in immediate early post-ischemic pro-inflammatory processes." (PMID 30722785, 2019). "Further, our results suggest that inhibition of EphB2 may specifically attenuate extrasynaptic NMDAR function, and thereby improve stroke outcome." (PMID 30722785, 2019).
systemic sclerosis (3 papers, 2021 to 2025). A chronic disorder, possibly autoimmune, marked by excessive production of collagen which results in hardening and thickening of body tissues. "Antibodies against EphB2 have been observed in both SLE and systemic sclerosis patients." (PMID 39027720, 2024).
Wilms tumor (3 papers, 2021 to 2024). An embryonal neoplasm characterized by the presence of epithelial, mesenchymal, and blastema components. "The findings indicated an elevated expression of EPHB2 in invasive Wilms tumors stages 2–4 compared to stage 1, suggesting that EPHB2 could serve as a marker for the invasive capacity of Wilms tumors." (PMID 38612645, 2024). "Furthermore, EphB2 had significantly lower expression in Wilms tumor tissues compared to normal kidney tissues, but its role in Wilms tumor requires further research." (PMID 35223830, 2022). "The investigation of EPHB2 gene expression by q PCR in 25 primary Wilms tumors revealed elevated EPHB2 expression in stages 2–4 compared to stage 1 Wilms tumors, probably showing a negative impact on carcinogenesis." (PMID 34445116, 2021).
abdominal aortic aneurysm (2 papers, 2012 to 2021). Enlargement and ballooning of the vessel that supplies arterial blood to the abdomen, pelvis and legs. "We examined the expression of ephrin-B1 and its cognate receptor EphB2, key regulators of angiogenesis and embryogenesis, in human abdominal aortic aneurysm (AAA) and analyzed their functional roles in cell migration." (PMID 22830028, 2012).
Arthritis (2 papers, 2020 to 2024). Inflammation of a joint. "Furthermore, attempts to induce arthritic lesions after chicken type II collagen administration fail totally in EphB2-deficient mice whereas all WT and half of the immunized EphB3−/− mice develop a typical collagen-induced arthritis." (PMID 38558087, 2024). "Finally, we identify ST6GALNAC1 as a marker of undifferentiated arthritis and MSA4A, PDZK1IP1 and EPHB2 whose expression profiles may potentially discriminate untreated early RA from UA and SLA." (PMID 32483203, 2020).
autism spectrum disorder (2 papers, 2017 to 2021). A spectrum of developmental disorders that includes autism, and Asperger syndrome. "This is in agreement with previous evidences by de novo mutations of GluN2B and EphB2 genes that have been identified in autism spectrum disorders." (PMID 31772302, 2021).
autoimmune disease (2 papers, 2020 to 2025). A disorder resulting from loss of function or tissue destruction of an organ or multiple organs, arising from humoral or cellular immune responses of the individual to their own tissue constituents. "Overall, these data indicate that EPHB2 is a promising target for EAE treatment, and these two existing drugs could potentially be used to treat Th17-mediated autoimmune diseases/inflammation, including MS." (PMID 32312989, 2020).
cholangiocarcinoma (2 papers, 2016 to 2022). A carcinoma that arises from the intrahepatic biliary tree (intrahepatic cholangiocarcinoma) or from the junction, or adjacent to the junction, of the right and left hepatic ducts (hilar cholangiocarcinoma). "Moreover, EphB2 expression was reported to be increased in cholangiocarcinoma (CCA) tissues." (PMID 35223830, 2022).
encephalitis (2 papers, 2017 to 2021). An acute inflammatory process affecting the brain parenchyma. "The interaction between NMDAR and EphB2 was found in anti-NMDAR encephalitis." (PMID 35069111, 2021). "Thus, microRNA-204 may play an important role in anti-NMDAR encephalitis by regulating EphB2-NMDAR, which remains to be explored." (PMID 35069111, 2021).
endometrial cancer (2 papers, 2019 to 2025). Primary or metastatic malignant neoplasm involving the endometrium (mucous membrane that lines the endometrial cavity). "Immunohistochemical data from the HPA database corroborated these findings, showing higher protein levels of EPHB2 in endometrial carcinoma compared to normal tissues." (PMID 41322437, 2025). "Notably, EPHB2 mRNA was significantly overexpressed in endometrial carcinoma." (PMID 41322437, 2025). "Among these survival-related genes, five genes (EPHB2, FBP1, NLRC3, PPP2R3A, and TRIM46) were included in a previously reported 9-gene signature for predicting endometrial cancer patient survival." (PMID 30847026, 2019).
fibrosarcoma (2 papers, 2019 to 2024). A malignant mesenchymal fibroblastic neoplasm affecting the soft tissue and bone. "We show that knocking down EphB2 or ERK in fibrosarcoma cells specifically leads to disruption of the repulsion phase of CIL in response to interactions with epithelial cells." (PMID 31076510, 2019). "This repulsion is prevented when EphB2 or ERK is knocked down in fibrosarcoma cells." (PMID 38396812, 2024).
fibrosis (2 papers, 2017 to 2024). the formation of excess fibrous connective tissue in an organ or tissue in a reparative or reactive process. "Moreover, offspring of HFD dams had altered methylation patterns in DMRs of genes that play important roles in hepatic fibrosis and lipid accumulation, including Ppargc1β, Fgf21, Ephb2 and VWF." (PMID 28414763, 2017).
fungal infection (2 papers, 2020 to 2025). "This study provides not only a mechanistic explanation for EPHB2 and Dectin-1 activation after fungal infection but also new insights into potential therapeutic strategies for treating IFIs." (PMID 40489568, 2025). "In this study, we show that EPHA5 plays a critical role in antifungal immunity by phosphorylating EPHB2 and Dectin-1 after fungal infection, which facilitates the recruitment and activation of Syk and subsequent activation of downstream antifungal signaling pathways." (PMID 40489568, 2025). "In an early study, we showed that EPHB2 is a coreceptor of β-glucan and phosphorylates Syk to activate the downstream signaling pathway, but how EPHB2 is activated after fungal infection is unknown." (PMID 40489568, 2025). "In the present study, we show that EPHA5 plays a critical role in the antifungal innate immune response by phosphorylating EPHB2 and Dectin-1 after fungal infection, which facilitates the recruitment and activation of Syk for downstream activation of antifungal signaling pathways." (PMID 40489568, 2025). "Previously, we reported that EPHB2 is a coreceptor of β-glucan and plays a critical role in innate antifungal immunity, but the detailed mechanism by which EPHB2 is activated after fungal infection is still unknown." (PMID 40489568, 2025). "Here, by using cellular and mouse fungal infection models, we report that EPHA5 is an upstream kinase for EPHB2 and Dectin-1 after fungal infection, which facilitates the subsequent activation of downstream antifungal signaling pathways." (PMID 40489568, 2025). "However, how EPHB2 is activated after fungal infection is still unknown." (PMID 40489568, 2025). "Here, we show evidence that, upon fungal infection, EPHA5 phosphorylates EPHB2 for its activation, which is critical for the activation of downstream signaling pathways." (PMID 40489568, 2025).
irritable bowel syndrome (2 papers, 2021 to 2022). Irritable bowel syndrome (IBS) is a chronic functional condition of the lower gastrointestinal (GI) tract characterized by abdominal pain or discomfort and disordered bowel habit (diarrhea, constipation, or fluctuation between the two). "Furthermore, a recent study showed that EphB2 was expressed on colonic enteric nerves and could regulate the expression of key molecules involved in synaptic sprouting of myenteric nerves via ERK-MAPK and PI3K–protein kinase B pathways in patients with irritable bowel syndrome." (PMID 34648765, 2021).
liver cirrhosis (2 papers, 2018 to 2024). "In most cases EphB2 proteins were elevated in liver cirrhosis but virtually undetected in normal liver." (PMID 29416088, 2018).
metabolic dysfunction-associated steatohepatitis (2 papers, 2021 to 2024). Metabolic dysfunction-associated steatohepatitis (MASH, formerly known as nonalcoholic steatohepatitis or NASH) is a type of fatty liver disease. "This included specific reductions in inflammatory genes, GPNMB, CCL3, MMP12, and EPHB2, which were up-regulated in humans and animal models of metabolic dysfunction-associated steatotic liver disease (MASLD) or metabolic dysfunction-associated steatohepatitis (MASH)." (PMID 39282008, 2024).
metastatic disease (2 papers, 2025). "While most of our results align with existing studies, the unique identification of mutations such as SAMD9L and ATP8B1 in metastatic tumors and gender-specific enrichment of CDK8 and EPHB2 are less commonly reported and may represent new areas for investigation in personalized therapeutics." (PMID 41590495, 2025).
rectal cancer (2 papers, 2008 to 2021). A primary or metastatic malignant neoplasm that affects the rectum.
rhabdomyosarcoma (2 papers, 2022 to 2024). A rare aggressive malignant mesenchymal neoplasm arising from skeletal muscle. "An increased expression of EPHs (EPHB1, EPHB2, EPHB3, and EPHB4) and their ephrin ligands (ephrin-B1 and ephrin-B2) has been implicated in promoting angiogenesis and tumor progression in rhabdomyosarcoma." (PMID 38612645, 2024). "Similarly, these oncogenic effects are demonstrated in soft tissue sarcomas when EPHA3, EPHB2 and EPHB4 stimulate properties such as proliferation, increased motility, migration, invasion and metastasis of rhabdomyosarcoma and synovial sarcoma cells." (PMID 35563562, 2022).
schizophrenia (2 papers, 2019 to 2021). A major psychotic disorder characterized by abnormalities in the perception or expression of reality. "Of note, several recent human genome-wide association studies identified EPHB2 as a possible risk gene for schizophrenia." (PMID 33649502, 2021). "The axon guidance- and synapse-related gene, EPHB2, has emerged as a potential risk gene for multiple neuropsychiatric disorders, including schizophrenia, depression, and anxiety disorders." (PMID 33649502, 2021). "The PPI deficit in the EphB2+/− mice suggests abnormalities in sensorimotor gating, and PPI deficits are observed in multiple neuropsychiatric disorders, including schizophrenia." (PMID 33649502, 2021).
small cell lung carcinoma (2 papers, 2019 to 2021). Small cell lung cancer (SCLC) is a highly aggressive malignant neoplasm, accounting for 10-15% of lung cancer cases, characterized byrapid growth, and early metastasis. "EPHB2, as an EPHB subgroup receptor kinase, could modulate the biological behavior of small cell lung carcinoma through autocrine and/or juxtracrine activation by ephrin-B ligands (EFNB1, EFNB2, and EFNB3) that are expressed in the same or neighboring cells." (PMID 34645436, 2021).
squamous cell carcinoma (2 papers, 2021 to 2024). A carcinoma arising from squamous epithelial cells. "Moreover, a significant increase in squamous cell carcinoma proteins marker genes such as SerpinA1, SerpinA3 and EphB2 under the influence of UV radiation was observed in cells with efficiently functioning NLRP1 and NLRP3." (PMID 39839625, 2024). "Compared with adenocarcinoma, squamous cell carcinoma showed strong communications with endothelial by the MIF/TNFRSF10D, EGFR/GRN, EGFR/HBEGF, and EPHB2/EFNB2 interactions." (PMID 34185421, 2021).
thymic neoplasms (2 papers, 2021 to 2024). "Notably, in the present study, thymic neoplasms demonstrated very weak and rare staining for EphB2." (PMID 34943502, 2021).
triple-negative breast carcinoma (2 papers, 2020 to 2025). An invasive breast carcinoma which is negative for expression of estrogen receptor (ER), progesterone receptor (PR), and human epidermal growth factor receptor 2 (HER2). "In CHO/EphB2, triple-negative breast cancer, and lung mesothelioma xenograft models, both Eb2Mab-12-mG2a and Eb2Mab-12-hG1 exhibited potent antitumor efficacy." (PMID 40943224, 2025).
amyotrophic lateral sclerosis (1 paper, 2021). Amyotrophic lateral sclerosis (ALS) is a neurodegenerative disease characterized by progressive muscular paralysis reflecting degeneration of motor neurons in the primary motor cortex, corticospinal tracts, brainstem and spinal cord. "For example, elevated EphA4 signaling results in neuronal damage in Alzheimer’s disease and amyotrophic lateral sclerosis (ALS), and the loss of EphB2/B3 signaling is implicated in skeletal malformations that cause cleft palate." (PMID 33277361, 2021).